GATA3 (GATA binding protein 3)
Diseases named in the same sentence as GATA3 in open-access papers (continued):
Sharing a sentence is not in itself a finding about the gene and the disease.
tumor (continued). "These hub biomolecules of tumor stroma network, AR, GATA2, miR-124, TOR1AIP1, ESR1, EGFR, STAT1, miR-192, GATA3, COL1A1, may give crucial information about tumorigenesis." (PMID 33907495, 2021). "Eight tumors (32.0%) were negative for GATA3 in ≥90% of tumor cells, and two (8.0%) tumors were completely negative for GATA3." (PMID 34829389, 2021). "Immunohistochemistry showed that the tumor cells were immunoreactive for GATA3, TTF1, and napsin A and nonimmunoreactive for p40." (PMID 33542845, 2021). "Also, in the model P8X26, the expression of 8 markers (i.e., Ki67, P63, GATA3, KRT5/6, KRT20, 34βE12, EGFR, and HER2) was similar between the original tumor and different generations." (PMID 35432811, 2021). "Thus, we identified GATA3 and GATA6 as important transcription factors with opposite expression and effects on tumor prognosis in patients with different BLCA stem cell subtypes." (PMID 33115513, 2020). "Immunohistochemically, the tumor cells expressed ER, PR, and GATA3; however, PAX8 was not expressed." (PMID 32164210, 2020). "Interestingly, further investigation via Tumor Immune Estimation Resource (TIMER) showed these transcriptional factors, particularly GATA3, were closely related to the immune cell infiltration of tumors." (PMID 33408272, 2020). "(F) Expression of the luminal markers, FOXA1 (1.8-fold increase) and GATA3 (1.8-fold increase), and the basal markers, CDH3 (6-fold decrease) and KRT6A (9-fold decrease) in tumor xenografts from mice treated with 5’-azacitidine compared to those of the vehicle control." (PMID 31036156, 2019). "A small portion of CK7 and/or GATA3 negative cases in our series later developed tumor metastasis; however, CK7 and GATA3 immunostains were not used to form the diagnoses of these metastases." (PMID 31718619, 2019). "The supplementary IHC assay revealed that both tumor cell types were positive for GATA-3 but negative for estrogen and progesterone receptors (ER and PR), despite the slight difference in the intensity of expression of GATA-3 in two tumors." (PMID 31109373, 2019). "Indeed, treatment of the tumor cells with EZH2 specific inhibitor EPZ-6438 more significantly increased the levels of luminal markers ERα, GATA3, and CK18 in 3D cultures than in 2D culture." (PMID 31704972, 2019). "GATA3 was preferentially present in tumor cells of mediastinal CHL rather than non-mediastinal origin (p = 0.000)." (PMID 31831043, 2019). "P63 expression in tumor cells, even focal expression, and no GATA3 is the most helpful feature in distinguishing PMLBCL from mediastinal CHL." (PMID 31831043, 2019). "In our study, genes, such as GATA3, ERBB4, RET, NAT1, and TFF3, typically more expressed in ER positive tumor samples, were also more expressed in stromal cells from ER positive as compared with ER negative tumors (defined by immunohistochemistry of malignant cells)." (PMID 31817155, 2019). "However, coexpression of GATA3 and CK5/6 was observed in 44 (48.35%) cases; of them 13 (14.29%) had diffuse coexpression (staining in >80% of tumor cells for both markers)." (PMID 31469885, 2019). "Thus, GATA3 and MIR17HG operate in particular T-cell malignancies as oncogenes or tumor suppressors." (PMID 29746601, 2018). "Interestingly, they found a pro-oncogenic gene expression signature in early neoplasia which was distinct from normal tissues and carcinoma (DCIS/IDC) including up-regulation of ERBB2, FOXA1, and GATA3." (PMID 29720211, 2018). "Tumor cell lines demonstrated varying ratios of Zc3h8 to Gata-3 levels, while stable overexpression did not decrease Gata-3 levels." (PMID 30041613, 2018). "Finally, TBX2 expression is positively correlated with GATA3, HAND2, and PHOX2B expression levels as well as with those of other potential CRC genes important in development in a NB tumor cohort (n = 283)." (PMID 30451831, 2018).
tumor (continued). "Second, Piwi-like 2 positivity was associated with a poorer DSS, OS and RFS in patients with tumor cells that are CK5-positive/GATA3-negative but not in those with GATA3-positive/CK5-negative tumor cells." (PMID 30523270, 2018). "Moreover, we found that, in clinical samples of HNSCC, the expression and distribution of GATA3 and HIF-1α are significantly correlated, implying that GATA3 can interact with HIF-1α in tumour cells to regulate their behaviours in vivo." (PMID 28263977, 2017). "Although the differentially expressed genes may represent both direct and indirect targets of GATA3 and HIF-1α, these results support that the GATA3/HIF-1α axis plays an important role in regulating tumour malignancy under hypoxia." (PMID 28263977, 2017). "Furthermore, the luminal category of tumours frequently express the transcription factors RXRA, PPARG, FOXA1, and GATA3, which are known to have a crucial role in urothelial differentiation." (PMID 28195647, 2017). "Moreover, tumour angiogenesis, one of the most recognized HIF-1-mediated response, was significantly increased in GATA3 overexpressing xenografts as shown by CD31 staining." (PMID 28263977, 2017). "In BCG failure, post-BCG tumor tissue analysis revealed no dynamic changes (mean ± SD) for GATA3 (199 ± 91.7), T-bet (64 ± 30.8) and GATA3/T-bet ratio (2.1 ± 1.8) compared to baseline." (PMID 28005163, 2017). "All cases of SC demonstrated S100, mammaglobin, and GATA-3 positive tumor cells and these markers were consistently negative in ACC." (PMID 28484662, 2017). "The second half showed significantly higher mRNA expression levels of the Uro‐diff gene signature, as well as of the key transcription factors FOXA1 and GATA3, and appeared to be indistinguishable from GU cases at the tumour‐cell level." (PMID 28195647, 2017). "Western blotting of 12 paired non-tumour/tumour tissues from HNSCC patients confirmed the GATA3 overexpression in HNSCC tumours (P<0.01)." (PMID 28263977, 2017). "Although the regulation of GATA3 on HIF-1α responsive genes is critical for tumour invasiveness under hypoxia and is emphasized in this study, GATA3 also regulates non-HIF-1α responsive genes, as shown in our functional pathway analysis." (PMID 28263977, 2017). "Furthermore, we identified the novel role of transcription factors GATA-2 and GATA-3 in suppressing MICA/B expression, which contributes to tumor escape from NK lysis." (PMID 27528231, 2016). "When we investigated this region using whole genome bisulfite sequencing data from TCGA, we found that CpGs near the GATA3 peak were unmethylated in breast but not in the other tumor types." (PMID 27833659, 2016). "Our results suggest that Gata3 is a tumor suppressor in B cells as opposed to a tumor promoter in T cells." (PMID 27588406, 2016). "When stratified by tumor size, the OS curves did not significantly differ between GATA3-positive and -negative cases among cases with tumors ≤ 5 cm (P = 0.0779)." (PMID 27249072, 2016). "These findingsprovide a complex picture of GATA3 function, whereby it mediates cellulardifferentiation in normal mammary gland, but becomes an essential component withinthe ER complex during tumour formation." (PMID 26884552, 2016). "We also tested tumour tissue from 10 luminal patient-derived xenograft (PDX) mouse models and did not detect any GATA3-ext mutations either." (PMID 27588951, 2016). "In the TCGA dataset, EHMT1 and EHMT2 are not differentially expressed in GATA3-ext tumours and do not show a segmentation pattern." (PMID 27588951, 2016). "This suggests that the expansion of Gata-3-Apc/Min+ Treg was more favored by the tumor microenvironment, giving more nonfunctional Treg." (PMID 26146642, 2015). "GATA3 was found to be localized in the nucleus, and the GATA3 immunoreactivity presented significant differences between the tumor tissue samples and the adjacent non-tumor tissue samples." (PMID 24504018, 2014).
tumor (continued). "Here we observed that this transcript is significantly elevated in early neoplasias compared to normal tissue using both 3SEQ and RNA in situ hybridization, and it shows correlated expression with the ER pathway members ER, FOXA1, and GATA3." (PMID 24887547, 2014). "However, it should be noted that two human luminal tumor-defining genes (XBP1 and GATA3, were both highly expressed in murine luminal tumors." (PMID 17493263, 2007). "Out of 11 ER target genes, four ER target genes showed significant differences between tumours with and without transcriptionally active NF-κB: GATA3 (P=0.001), MYB (P=0.004), HSD17β4 (P=0.030) and STARD10 (P=0.013)." (PMID 17700572, 2007). "We detected a strong correlation between the lack of GATA3 expression and higher histological tumor grade (poorly differentiated) demonstrated by multivariate (τb = -0.49; p = 0.002) and univariate (p = 0.004) analyses." (PMID 17078870, 2006). "On the other hand, molecular markers such as GATA3 provide insights at the molecular level, but these tests typically require invasive tissue sampling and may not adequately capture the tumor’s spatial heterogeneity in real-time." (PMID 40881878, 2025). "No KIT, CD10, CA9, GATA3 or alpha-methylacyl-CoA racemase was detected in the tumor cells." (PMID 39980061, 2025). "Regarding mechanism, IL-33 activates the p38- GATA binding protein 3 (GATA3) signaling pathway to induce M2 polarization of macrophages, promote Th2 cells and ILC2 to secrete tumor-promoting cytokines, mainly IL-4, IL-5, and IL-13, thereby playing a role in promoting tumor development." (PMID 39925809, 2025). "Furthermore, we explore potential co-expression patterns or correlations between SOX9, GATA3, and GATA4, which may reflect shared regulatory pathways or converging roles in tumor differentiation, plasticity, or stromal remodeling." (PMID 41303462, 2025). "Specifically, high GATA3 expression in Luminal A and Luminal B subtypes is often correlated with a favorable prognosis, whereas low or absent expression may indicate higher tumor aggressiveness." (PMID 40881878, 2025). "The immunohistochemical analysis demonstrated partial positivity for GATA3 and p63, diffuse positivity for cytokeratin, β-catenin, and β-HCG, and Ki-67 proliferation index of 50x%, confirming the diagnosis and distinguishing the tumor from other trophoblastic diseases." (PMID 40958863, 2025). "GATA3 expression was significantly lower in the tumor tissue compared to the control for both responders and non-responders, while the gene expression was significantly higher in tumor tissue of the responders compared to non-responders." (PMID 40736702, 2025). "The tumor cells showed patchy positivity for cytokeratin 7 (CK7), strong cytoplasmic staining for alpha-methyl acyl-CoA racemase (AMACR), and were negative for PSA, cytokeratin 20 (CK20), GATA-binding protein 3 (GATA3), tumor protein 63 (p63), and caudal-type homeobox transcription factor 2 (CDX2)." (PMID 40662003, 2025). "This tumour also contained small foci of glandular differentiation and squamous morphology, both of which lacked expression of neuroendocrine markers but retained GATA3 expression indicating urothelial differentiation in this context." (PMID 40525454, 2024). "The stable expression of Gata3 in the total ILC2s across different conditions remained mostly unchanged (log2FC < 0.01) suggesting that ILC2 largely maintained their type 2 identity during tumour development and activation, at least at the transcriptional factor level, in the lungs." (PMID 38172434, 2024). "In addition, OLA treatment of Gata3 knockdown tumor cells, not control cells, also resulted in a significant reduction of the cell number." (PMID 38627785, 2024). "Notably, deletion of Fra1, like reconstitution of Gata3, in Gata3 deficient tumor cells inhibits EMT, preventing tumorigenesis and/or metastasis, whereas reconstitution of c-Fos in Gata3 deficient cells fails to inhibits EMT during tumorigenesis." (PMID 37353480, 2023).
tumor (continued). "However, CXCL8, which promoted tumor invasion and angiogenesis, was not significantly down-regulated in the high-GATA3 group." (PMID 35647011, 2022). "To verify this previously unknown cell-of-origin for pRCC, we recruited an independent pRCC cohort of 50 patients from Drum Tower hospital and performed immunofluorescence staining with the PT marker AQP1, the CD_PC marker GATA3 or GRHL2, on tumor samples from these patients." (PMID 35013217, 2022). "In contrast, GATA3 inactivation did not affect Th9-mediated tumour growth." (PMID 35793807, 2022). "In all cases tested, the tumor cells were positive for PAX8 (2/2, diffusely in both), GATA3 (4/4, diffusely in two and focally in two), and TTF1 (3/3, focally in two and diffusely in one), and the one (case 3) which was diffusely positive for TTF1 also diffusely expressed GATA3." (PMID 35865471, 2022). "However, the tumor cells were negative for GATA3, mammaglobin, ER, PR, HER2, CK20, chromogranin, and CD56." (PMID 35029184, 2022). "In addition, GATA3, ERBB4, RET, NAT, and TFF3 genes are commonly expressed in tumor cells, which may also influence response to treatment." (PMID 36536751, 2022). "The tumor-infiltrating RORC-Tregs we have shown to be linked to poor patient outcomes and associated with tumor androgenesis were selected based on elevated levels of FOXP3, CTLA4, GITR, RORC and GATA3 transcripts in the whole tumor, not from individual T-cells." (PMID 34681642, 2021). "Moreover, SMR3B gene (submaxillary gland androgen-regulated protein 3B) was identified to have differential expression between GATA3 mutant and non-mutant tumor tissues as mutant samples indicate a lower level of expression." (PMID 33462316, 2021). "The tumor cells were positive for PAX2 but negative for GATA3." (PMID 33919505, 2021). "According to existing reports, increased Th2 marker levels accelerate the secretion of interleukin(IL)-10 and IL-4 and inhibit cellular immune function, and the GATA3/T-bet(G/T) ratio of tumor-infiltrating lymphoid cells is an independent negative predictive marker for survival." (PMID 34221962, 2021). "Also, differential gene expression analysis has identified different patterns of expression in normal samples, GATA3 mutant and non-mutant tumor tissues in the entire cohort as well as in the ER-positive cases." (PMID 33462316, 2021). "Results indicated that 116 and 95 genes (proteins) for all patients and 142 and 191 for ER-positive subgroup matched the database and were used to construct the PPI network between GATA3 mutant tumor and normal tissues and between GATA3 non-mutant tumor and normal tissues, respectively." (PMID 33462316, 2021). "However, the tumor was diffusely and strongly positive for the expression of p16 and negative for the expression of GATA-binding protein 3 (GATA3)." (PMID 33919505, 2021). "The tumor cells expressed synaptophysin, cytokeratin MNF 116,cytokeratin 5/6 (CK5/6), cell adhesion molecule 5.2 (CAM5.2), p40, p63, without expression of thyroidtranscription factor 1 (TTF-1), GATA binding protein 3 (GATA3), chromogranin A, CD56, CD45, orS100." (PMID 34106022, 2021). "Since GATA3 mutants compared with non-mutant tumor samples did not indicate any difference in expression of MYH2, its lower expression in tumor samples may be resulted due to the tumor environment." (PMID 33462316, 2021). "Immunostains showed the cells had patchy positivity for Pax‐8 and GATA‐3, and focal weak positivity for pancytokeratin and p63, while they were negative for TTF‐1, CK7, CK20, CA‐IX, and 34‐beta‐E‐12, compatible with a metastasis from a sarcomatoid neoplasm of renal origin." (PMID 32463173, 2020).
tumor (continued). "CNGs associated with poor outcome harboured transcription factors GATA3, GATA5, MLLT10, and TAF3 frequently amplified in HBCs15,19,28,41–43, EMT markers VIM, LAMA5, and ZEB121, and several genes enriching biological processes enhancing tumour-cell migration and motility." (PMID 31969654, 2020). "Whilst our emphasis has been on the Akt-GSK-3β pathway, it is also possible that other kinases may facilitate the phosphorylation of GATA3, given the signalling intricacies of tumour cells, with PKA and p38 MAPK both previously identified as facilitating GATA3 phosphorylation." (PMID 33298139, 2020). "While it has be shown that GATA3 is required for the stabilization of a hypoxic microenvironment through binding with HIF1-α, this current study shows the possible role of GATA 2 and GATA3 in altering the glycosylation of tumor glycoproteins, thereby potentially contributing to cell invasiveness." (PMID 32850359, 2020). "Differential analysis of tumor versus healthy biopsies highlighted 166 candidate genes with different DNA methylation levels in their promoters, which included the tumor-specific hypomethylated EGFL8 promoter as well as hypermethylated promoters of ESR1, PTGIS, and GATA3." (PMID 30645971, 2019). "The GATA3 expression level was 15,000 in tumor tissues and 5000 in normal tissues." (PMID 31182966, 2019). "On the contrary, GATA3+ T helper 2 (Th2) cells and FOXP3+ regulatory T lymphocytes (Tregs) downregulate antitumor immune response by impairing antigen presentation, activity, and cytotoxicity of other immune cells, thus promoting tumor growth and immune tolerance." (PMID 31016433, 2019). "FOXC1 and GATA3 appear to be involved in a double-negative-feedback loop (mutual inhibition) that may influence the transition between luminal-like and basal-like tumor phenotypes." (PMID 27539783, 2016). "Thus, tumor cells acquire mesenchymal characteristics in the absence of miR-573, even with high levels of GATA3 expression." (PMID 26451614, 2015). "However, it has been also postulated that GATA3 defines a distinct class of cancer genes that are differentiation factors rather than conventional tumor suppressor genes, which affect the malignant phenotype by enforcing differentiation." (PMID 24758297, 2014). "Similarly, analysis of FOG-2, GATA-2 and GATA-3 expression by real-time RT-PCR disclosed only lower FOG-2 levels in MYCN-amplified vs MYCN-nonamplified tumours at a significant level." (PMID 19707195, 2009). "Two main groups were identified, one over-expressing markers typically found in sporadic luminal tumours such as GATA3, TFF1 and SCUBE2, and the other negative for ESR1, ERBB2 and the PR gene (PGR) (triple negative) and over-expressing genes from the basal layer such as CDH3, CRYAB and KRT5-17." (PMID 19826428, 2009). "Indeed, ER+ tumours were scattered in subgroups 1 to 4 that are characterised by the over-expression of a cluster of genes, which includes CCND1, KRT19, IGF1R, LIV1, ESR1, GATA3, TFF1/pS2, ERBB4, PR and IGFBP4." (PMID 17338809, 2007). "Furthermore, the incidence of poor prognosis events was significantly lower in GATA3-positive patients compared to GATA3-negative ones, further supporting the hypothesis of its potential tumor-suppressive role." (PMID 40881878, 2025). "An increase in the betweenness centrality of a node/gene in tumor samples indicates that the gene lies on shorter paths connecting other genes, suggesting its role as a bridge in tumor-related PPIs, for instance, VCL, FLNA, TNS1, GATA3, and ITGB3, which may act as key connectors in tumor samples." (PMID 40626556, 2025). "Additionally, GATA3 has been observed to function as a proto-oncogene in many T-cell tumor types, including precursor neoplasms, without concurrent expression of other Th2-specific genes, further challenging the ontological relationship between GATA3-expressing PTCLs and Th2 cells." (PMID 38166662, 2024).